HDAC4 (histone deacetylase 4)
Diseases named in the same sentence as HDAC4 in open-access papers (continued):
Sharing a sentence is not in itself a finding about the gene and the disease.
bladder cancer (8 papers, 2011 to 2024). "We identified four key genes, HDAC4, TRIM27, EGR2, and UBE2I, that exhibited significant associations with bladder cancer prognosis." (PMID 38911380, 2024). "The results indicated that among 411 cases of bladder cancer, TRIM27 gene mutations were detected in 5 patients, HDAC4 gene mutations in 4 patients, EGR2 mutations in 2 patients, and UBE2I gene mutations in 1 patient." (PMID 38911380, 2024). "Our findings demonstrated that four genes, HDAC4, TRIM27, EGR2, and UBE2I, exhibited significant associations with bladder cancer prognosis." (PMID 38911380, 2024). "This suggests that HDAC4, TRIM27, EGR2, and UBE2I exhibit a relatively low mutation rate in bladder cancer." (PMID 38911380, 2024). "Gene mutation analysis indicated a relatively low mutation rate in HDAC4, TRIM27, EGR2, and UBE2I in bladder cancer." (PMID 38911380, 2024). "No specific investigations on the ZNF516 repressor in bladder cancer have been published, whereas several investigations suggest that the class IIA histone deacetylase HDAC4 inhibits neoplastic properties of bladder cancer cells." (PMID 34885146, 2021). "In contrast, the expression levels of HDAC4 were greatly increased in most of the tested bladder cancer cells except the HTB4 bladder cancer cells in comparison to that of the GM00637 normal human fibroblast cells." (PMID 21507255, 2011). "To further verify our hypothesis, we transfected bladder cancer T24 cell with designed si HDAC4, si NFATC1 and si CBX7." (PMID 34405021, 2021). "We analyzed gene expression and prognostic value of SPRG and developed a SPRG signature (SPRGS) prognostic model based on four genes (HDAC4, TRIM27, EGR2, and UBE2I) in bladder cancer." (PMID 38911380, 2024). "To validate the IHC result, we further determined expression of several HDACs, including HDAC4, HDAC1, and HDAC2, in the HTB4, HTB9, HTB2, HTB3, HTB5, HT1197 and HT1376 bladder cancer cells." (PMID 21507255, 2011). "Notably, high expression levels of HDAC4 and TRIM27 were identified as favorable prognostic factors for bladder cancer patients, while elevated expression of EGR2 and UBE2I was associated with an unfavorable prognosis." (PMID 38911380, 2024). "All of these results suggest that over-expression of the HDAC4 contributes to the XPC gene silencing and the development of bladder carcinomas, and inhibiting the HDAC activities with the HDAC inhibitor VPA sensitizes the bladder carcinoma cells to anticancer drug cisplatin." (PMID 21507255, 2011).
muscle atrophy (8 papers, 2016 to 2025). The loss of muscle tissue due to inactivity or disease. "Considering the central role in mediating skeletal muscle nerve response, several studies indicated HDAC4 as a potential therapeutic target for the prevention of neurogenic muscle atrophy in pathological conditions or during aging." (PMID 29477142, 2018). "In addition, our results indicate that leucine is dominant in blocking HDAC4 signaling and highlight the use of this amino acid as a therapeutic tool in conditions involving skeletal muscle atrophy." (PMID 40183248, 2025). "Though there was no report on 4HR and age-associated muscle atrophy, 4HR administration decreased the expression level of HDAC4 in both HUVECs and Saos-2 cells." (PMID 35103875, 2022). "Through the study of the potential mechanism of HDAC4 in the process of muscle atrophy, we can provide an experimental basis for the discovery of new targets for the prevention and treatment of denervation-induced muscle atrophy." (PMID 34276308, 2021). "Moreover, treatment with the antioxidant drug Trolox prevented loss of muscle integrity and inflammation in in mice lacking HDAC4 in skeletal muscle, despite the resistance to neurogenic muscle atrophy." (PMID 29477142, 2018). "Taken together, HDAC4 inhibition can alleviate denervation-induced muscle atrophy by reducing MYOG expression, and HDAC4 is also directly related to CDKN1A and SIK1 in skeletal muscle, which suggests that HDAC4 inhibitors may be a potential drug for the treatment of neurogenic muscle atrophy." (PMID 34276308, 2021).
myocardial infarction (8 papers, 2018 to 2025). Gross necrosis of the myocardium, as a result of interruption of the blood supply to the area, as in coronary thrombosis. "Additionally, GWAS have associated single nucleotide polymorphisms (SNPs) in miR-140-5p gene targets such as SEPT2 (SEPTIN2) with T1DM, DNMT1 with CVD and HDAC4 with increased susceptibility to myocardial infarction following coronary artery bypass surgery." (PMID 36277770, 2022). "More specifically, HDAC4 overexpression exacerbated post-myocardial infarction cardiac dysfunction, remodeling, and interstitial fibrosis, owing to lowered heart cardiokine levels." (PMID 39281832, 2024). "In animal models, overexpression of HDAC4 increased myocardial infarct size, on the other hand, inhibition of HDAC4 stimulates regeneration and restoration of cardiac function and reduces myocardial infarction in ischemic HF." (PMID 36440025, 2022). "Inhibition of HDAC4 can improve cardiac function and reduce myocardial infarction in mice suffering from ischemic-induced heart failure." (PMID 34526481, 2021). "A recent study revealed that exercise improves cardiac function and glucose metabolism in mice with experimental myocardial infarction by inhibiting phosphorylated histone deacetylase 4 (HDAC4) and upregulating glucose transporter 1 (GLUT1) expression." (PMID 33354250, 2020). "The data suggest that HDAC4 overexpression in the heart increased myocardial infarct size." (PMID 30134825, 2018).
Cerebral ischemia (7 papers, 2015 to 2025). Restriction of arterial blood supply to the brain associated with insufficient oxygenation to support the metabolic requirements of the tissue. "Since protein phosphorylation has been implicated in the regulation of HDACs activity, we further detected the levels of phosphorylated HDAC4 after cerebral ischemia." (PMID 28127553, 2017). "We first measured the expression change of HDAC4 in a cell hypoxia model which mimics the pathophysiology of cerebral ischemia." (PMID 28127553, 2017). "In this study, we use rat tMCAO model and found that the expression of HDAC4 was unaltered after cerebral ischemia, but phosphorylation of HDAC4 was significantly upregulated in MCAO rats." (PMID 28127553, 2017). "In summary, our in vivo and in vitro studies demonstrated that HDAC4 is phosphorylated after cerebral ischemia." (PMID 28127553, 2017). "Collectively, our in vivo and in vitro results indicate that HDAC4 is functioned in a phosphorylated way and plays an important role in neovascularization induced by cerebral ischemia." (PMID 28127553, 2017). "The results of this study have identified the mechanisms by which HDAC4 serves as an important HIF-VEGF signal-sensitive molecule to modulate angiogenesis responses to cerebral ischemia." (PMID 28127553, 2017). "In support of this hypothesis, we found that the HIF-VEGF signal was activated in ischemic regions after cerebral ischemia, and the phosphorylated HDAC4 protein was remarkably increased after the activation of HIF-VEGF signaling." (PMID 28127553, 2017). "Taken together, these results demonstrate that phosphorylated HDAC4 may play a functional role in angiogenesis after cerebral ischemia." (PMID 28127553, 2017). "Our data along with published studies suggest that phosphorylated HDAC4 may play a functional role in cerebral ischemia." (PMID 28127553, 2017). "HDAC5 and HDAC4 were markedly reduced in both cerebral ischemia/reperfusion injury and OGD model, and NADPH oxidase-reduced HDAC4 and HDAC5 accelerates cerebral ischemia injury via increasing the expression and release of high mobility group box-1 protein (HMGB1)." (PMID 27330844, 2016). "However, whether HDAC4 is involved in the regulation of angiogenesis after cerebral ischemia remains largely unexplored." (PMID 28127553, 2017). "It is observed that HDAC4 down-regulation increases angiogenesis through stimulation of VEGF-B gene expression, and it has also been reported in the cerebral ischemia that higher expression of the HIF-VEGF signaling gene has be seen through the phosphorylation of the HDAC4 protein." (PMID 33806202, 2021). "Western blot experiments showed that phosphorylated HDAC4 in the right ischemic cortex was remarkably increased after cerebral ischemia when compared with the left nonischemic cortex (P < 0.05)." (PMID 28127553, 2017). "It demonstrates a role for phosphorylated HDAC4 mediated HIF-VEGF signal and regulated HIF-VEGF downstream genes expression in cerebral ischemia, which may provide novel therapeutic target for cerebral ischemia." (PMID 28127553, 2017). "While it is reported that the down-regulation of HDAC4 increases the expression of the VEGF-B gene and angiogenesis, the higher expression of the HIF-VEGF signaling gene through the phosphorylation of the HDAC4 protein in the cerebral ischemia has been also reported." (PMID 30186566, 2018).
depression (7 papers, 2016 to 2025). "Recent studies highly suggest that HDAC4 is implicated in the pathology of depressive disorders." (PMID 27847464, 2016). "Furthermore, depression is a common feature in AD, which may be associated with the increase of HDAC4 expression in AD patients." (PMID 27847464, 2016). "Chronic stress enhances the function of HDAC2, which inhibits the transcription of glial cell-derived neurotrophic factor (GDNF) and thus induces depression; abnormal expression of HDAC4/5 and subsequent abnormal acetylation of histones leads to depression." (PMID 37140907, 2023). "A previous study has reported that hippocampal administration of HDAC4/5 inhibitors prevented chronic stress-induced depressive behavior, which can be considered a new treatment strategy for depression." (PMID 36583185, 2022). "Ectopic overexpression of HDAC4 in hippocampus is sufficient to induce depression-like behavior in adult mice, indicating that HDAC4 elevation is the key to induce depression-like behavior." (PMID 27847464, 2016). "First, aberrant expression of HDAC4 mRNA has been detected in patients with depression." (PMID 27847464, 2016). "Intriguingly, adult fluoxetine application does not induce depression-like behavior in mice which is associated with unchanged HDAC4 expression." (PMID 27847464, 2016). "In addition, HDAC4 mRNA is significantly increased in brains of forced-swim stress-induced- and postnatal fluoxetine-induced depression model mice." (PMID 27847464, 2016). "Consistently, antidepressant reduces the recruitment of HDAC4 to the glial cell-derived neurotrophic factor (GDNF) promoter, consequently increasing the expression of GDNF which is reduced in patients with depression." (PMID 27847464, 2016). "Similarly, HDAC4 and HDAC5 are also overexpressed in depression." (PMID 36583185, 2022).
Hyperglycemia (7 papers, 2015 to 2025). An increased concentration of glucose in the blood. "Even though the HDAC4 p.E374K variant in this family has a relatively high allele frequency of the South Asian, the allele frequency in European is quite rare, indicating both population heterogeneity and the incomplete penetrance of this variant to the hyperglycemia." (PMID 30968599, 2019). "In contrast, overexpression of miR-29a promotes nephrin acetylation that ameliorates hyperglycemia-induced podocyte dysfunction through inhibition of HDAC4 signaling transduction." (PMID 26305546, 2015). "Blockade of HDAC4 signaling increased the H3K9Ac levels in the miR-29a proximal promoter and miR-29a transcription in hyperglycemia-treated podocytes and attenuated the hyperglycemia-induced apoptosis." (PMID 36983082, 2023). "In comparison with individual datasets, 2 hypomethylated genes (HDAC4 and KCNQ1) were commonly found in the hyperglycemia-treated VAL3 and the Dayeh’s study." (PMID 34639069, 2021).
Intellectual disability (7 papers, 2014 to 2025). "Mutations within the 14-3-3 binding site of HDAC4 have been identified in seven unrelated individuals with intellectual disability and developmental delay, and these mutations reduce the affinity of HDAC4 for 14-3-3 in cultured cells." (PMID 41151763, 2025). "Heterozygous deletion of 2q37, a chromosomal region including HDAC4, is associated with neurological features including developmental delay, intellectual disability and autism." (PMID 38167120, 2024). "More recently histone deacetylase 4 (HDAC4) was implicated in children with intellectual disability." (PMID 33327934, 2020). "Haploinsufficiency of HDAC4 is also associated with mental retardation in humans suggesting that the roles identified for HDAC4 in mice are likely conserved in humans." (PMID 30283297, 2018). "The Mef2-HDAC4 complex has also been implicated in synaptic plasticity and a truncated variant of HDAC4 has been associated with mental retardation." (PMID 24714615, 2014). "Disruption to the subcellular regulation of HDAC4 has also been implicated in CDKL5 disorder, in which mutations in cyclin dependent kinase-like 5 (Cdkl5) cause severe intellectual disability and motor impairment." (PMID 38167120, 2024). "HDAC4 -is considered responsible for many of the phenotypical findings in 2q37DS, including brachymetaphalangy and intellectual disability, behavioral disorders, and seizures." (PMID 36833393, 2023). "Five individuals sharing similar clinical features including developmental delay, hypotonia and intellectual disability were all identified to carry de novo heterozygous missense substitutions in HDAC4 14–3-3 binding sites predicted to result in its nuclear translocation." (PMID 38167120, 2024).
ischemia (7 papers, 2018 to 2025). A hypoperfusion of the BLOOD through an organ or tissue caused by a PATHOLOGIC CONSTRICTION or obstruction of its BLOOD VESSELS, or an absence of BLOOD CIRCULATION. "Using IR-induced AKI and CKD mouse models, we found that HDAC4 is rapidly activated following acute ischemia and remains persistently elevated during chronic fibrotic phases." (PMID 41282137, 2025). "Exercise enhances cardiac function and glucose metabolism in HF mice post-MI induced by ischemia by inhibiting HDAC4 and increasing GLUT1 expression via AMPK-HDAC4-MEF2a pathway activation." (PMID 37965091, 2023). "This suggests that activation of HDAC4 increased infarct size in response to ischemia and reperfusion injury." (PMID 30134825, 2018). "Therefore, we sought to include trichostatin A to see whether the physiological function of cardiac HDAC4 would be affected in response to ischemia and reperfusion injury." (PMID 30134825, 2018). "Other HDACs can also negatively affect cardiac functioning: overexpression of HDAC4 in mouse cardiomyocytes reduced functional recovery after ischemia/reperfusion injury, while excessive activity of HDAC6 in diabetic rats increased their vulnerability to ischemia/reperfusion injury." (PMID 34884505, 2021). "HDACs’ class II sometimes can have controversial roles: The overexpression of HDAC4 in mouse ischemia/reperfusion model resulted in reduced myocardium recovery and excessive activity of HDAC6 in diabetic rats was also related to increased vulnerability to ischemia/reperfusion injury." (PMID 32650632, 2020).
asthma (6 papers, 2018 to 2025). "Our results highlight a novel mechanism of miR-22 mediated suppression of CD147 and HDAC4 in airway epithelial dysregulation that is associated with IAV H1N1 infection in severe asthma." (PMID 30068332, 2018). "With an attempt to test the underlying mechanism of HDAC4 in the process of asthma, we infected human bronchial epithelial BEAS-2B and HBE cells with lentivirus sh-HDAC4 to inhibit the expression of HDAC4." (PMID 34118928, 2021). "In the current study, we explored the contributory role of HDAC4-mediated KLF5/Slug/CXCL12 axis in the development of asthma." (PMID 34118928, 2021). "Collectively, HDAC4 deacetylates KLF5 to upregulate Slug and CXCL12, thereby causing airway remodeling and facilitating progression of asthma." (PMID 34118928, 2021). "We conducted this study aiming at exploring the effect of Histone deacetylase 4 (HDAC4)-mediated Kruppel-like factor 5 (KLF5)/Slug/CXC chemokine ligand-12 (CXCL12) axis on the development of asthma in regulation of airway inflammation and remodeling." (PMID 34118928, 2021). "Moreover, HDAC4 was revealed to be responsible for allergic inflammation in HMC-1 cells during asthma." (PMID 34118928, 2021). "Our study suggests that activation of AMPK modulates miR-206/HDAC4/cyclin D1 signaling pathway, particularly targeting on HDAC4, to suppress ASMCs proliferation and therefore has a potential value in the prevention and treatment of asthma by alleviating airway remodeling." (PMID 29483552, 2018). "In addition, we found that HDAC4 deacetylated KLF5 to promote its transcription in asthma." (PMID 34118928, 2021). "Moreover, the suppression of HDAC4 could participate in a miR-220-mediated self-defense mechanism against abnormal epithelial responses in asthma." (PMID 34118928, 2021). "For example, histone deacetylase 4 can mediate KLF5 deacetylation to upregulate CXCL12, leading to airway remodeling and promoting the progression of asthma." (PMID 35619697, 2022). "In this part of the study, we constructed a mouse model of asthma induced by OVA and injected sh-HDAC4 and CXCL12 lentiviruses into the model mice via a tail vein." (PMID 34118928, 2021). "We thus conclude that the interaction between HDAC4 and KLF5 through deacetylation plays an important role in asthma development." (PMID 34118928, 2021). "The mice were sham-operated, asthma induced with OVA, or induced with OVA and further treated with sh-NC or sh-HDAC4 for subsequent animal experiments." (PMID 34118928, 2021). "In severe asthma, miR-22 expression, along with its targets CD147 and HDAC4, is dysregulated by the influenza virus, which may explain the H1N1 influenza infection-induced airway remodeling in severe asthma." (PMID 34566492, 2021). "Indeed, roles for other epigenetic effectors, including histone methylation and acetylation marks, have been implicated in the severity of asthma, and a genome-wide association study identified significant histone modifying enzyme (KDM2A, KDM4C, HDAC4, HDAC7 and HDAC9) polymorphisms in asthma." (PMID 40057553, 2025).
atherosclerosis (6 papers, 2021 to 2025). A disease characterized by the build-up of fatty material and calcium deposition in the arterial wall resulting in partial or complete occlusion of the arterial lumen. "Promotion of ox-LDL-induced endothelial apoptosis and subsequent atherosclerosis progression may be caused by the upregulation of miRNA-200 via targeting of HDAC4." (PMID 40002927, 2025). "Histone deacetylase 4 (HDAC4) is engaged in the pathophysiology of acute ischemic stroke (AIS) through modulating atherosclerosis, inflammation and neurocyte death." (PMID 35353946, 2022). "Additionally, in atherosclerosis, miR‐200b‐3p has been found to enhance endothelial cell injury through targeting HDAC4." (PMID 35261213, 2022). "Mechanistically, miR-300b-3p targets histone deacetylase 4 (HDAC4) as the overexpression of HDAC4 reduced the increased apoptosis induced by inhibiting miR-200b-3p, suggesting that miR-200b-3p is a potential therapeutic target for atherosclerosis." (PMID 36428980, 2022).